TAF11 (TATA-box binding protein associated factor 11)
Description:
The TFIID basal transcription factor complex plays a major role in the initiation of RNA polymerase II (Pol II)-dependent transcription. TFIID recognizes and binds promoters with or without a TATA box via its subunit TBP, a TATA-box-binding protein, and promotes assembly of the pre-initiation complex (PIC). The TFIID complex consists of TBP and TBP-associated factors (TAFs), including TAF1, TAF2, TAF3, TAF4, TAF5, TAF6, TAF7, TAF8, TAF9, TAF10, TAF11, TAF12 and TAF13. TAF11, together with TAF13 and TBP, play key roles during promoter binding by the TFIID and TFIIA transcription factor complexes.
Synonyms: TAFII28; TAF2I; PRO2134; MGC:15243
Tractability: Small molecule: a structure with a bound ligand is known. PROTAC: ubiquitination databases record sites on it; a small molecule that binds it is known.
Target class: Transcription factor
Gene: Protein-coding gene on chromosome 6 (34,877,462 to 34,889,192, reverse strand). Ensembl gene ENSG00000064995.
Subcellular location: Nucleus
Subcellular location (Human Protein Atlas): Nucleoplasm; Golgi apparatus
Pathways (Reactome):
Gene expression (Transcription): RNA Polymerase II Pre-transcription Events; RNA Polymerase II Promoter Escape; RNA Polymerase II Transcription Initiation; RNA Polymerase II Transcription Initiation And Promoter Clearance; RNA Polymerase II Transcription Pre-Initiation And Promoter Opening; RNA polymerase II transcribes snRNA genes
Disease: HIV Transcription Initiation; RNA Polymerase II HIV Promoter Escape; Transcription of the HIV genome
Gene Ontology:
Molecular function: nuclear thyroid hormone receptor binding; nuclear vitamin D receptor binding; protein binding; TBP-class protein binding; transcription coactivator activity; RNA polymerase II general transcription initiation factor activity; DNA binding; protein heterodimerization activity
Biological process: host-mediated activation of viral transcription; mRNA transcription by RNA polymerase II; positive regulation of transcription initiation by RNA polymerase II; RNA polymerase II preinitiation complex assembly; transcription by RNA polymerase II; transcription initiation at RNA polymerase II promoter
Cellular component: nucleoplasm; nucleus; transcription factor TFIID complex
Genetic constraint (gnomAD): Loss-of-function variants: 9 observed, 23.93 expected, observed/expected ratio (o/e) 0.38, 90% interval 0.23 to 0.66. The upper end of that interval is the gene's LOEUF score, 0.66, which puts it in group 2 of 6, group 1 being the genes least tolerant of losing a copy. Missense variants: 183 observed, 262.86 expected, observed/expected ratio (o/e) 0.7, 90% interval 0.62 to 0.79. Synonymous variants: 77 observed, 98.69 expected, observed/expected ratio (o/e) 0.78, 90% interval 0.65 to 0.94.
Homologues: Orthologues: chimpanzee TAF11 (99% identical), macaque TAF11 (97% identical), pig TAF11 (92% identical), rabbit TAF11 (92% identical), dog TAF11 (90% identical), guinea pig TAF11 (88% identical), mouse Taf11 (87% identical), rat Taf11l1 (85% identical), rat Taf11 (71% identical), tropical clawed frog taf11 (61% identical), zebrafish taf11 (59% identical), Drosophila melanogaster Taf11 (46% identical), and 2 more. Paralogues in human: TAF11L2 (58% identical), LINC02218 (57% identical), TAF11L12 (55% identical), TAF11L11 (55% identical), TAF11L13 (54% identical), TAF11L4 (54% identical), TAF11L10 (53% identical), TAF11L5 (53% identical), TAF11L6 (53% identical), TAF11L7 (53% identical), TAF11L8 (53% identical), TAF11L3 (53% identical), and 2 more.
Diseases named in the same sentence as TAF11 in open-access papers:
TAF11 is named in the same sentence as 4 diseases in open-access papers, as found by Europe PMC text mining. Sharing a sentence is not in itself a finding about the gene and the disease. The quoted sentences say what the papers report.
Hepatitis (1 paper, 2010). Inflammation of the liver. "GRB2 and HSPA1A and B genes directly act on angiogenesis, TAF11 is known to be involved in artery passage, and the E2F1 transcription factor is known to be an angiogenesis positive inducer in hepatitis and cancer." (PMID 20426824, 2010).
cancer (2 papers, 2010 to 2019). A tumor composed of atypical neoplastic, often pleomorphic cells that invade other tissues. "This revealed a sub-network linking eight transcriptional regulators of which most already have been related to cancer progression, including HDAC2, BPTF, BRF1, TAF11, TCF12, and FOS31,32, but also a prominent role for SMADs that are normally driven by TGF-β33." (PMID 31278301, 2019).
TAF11 also shares sentences with these, for which no sentence is quoted: infection (1 paper); oligodendroglioma (1).